MAPT (microtubule associated protein tau)
Diseases named in the same sentence as MAPT in open-access papers (continued):
Sharing a sentence is not in itself a finding about the gene and the disease.
Alzheimer disease (continued). "Alzheimer’s disease (AD), the most common cause of dementia, is characterized by the deposition of two different protein aggregates: (a) senile amyloid-β (Aβ) plaques and (b) neurofibrillary tangles of the microtubule-associated protein tau." (PMID 34689261, 2022). "MAPT protein (the hallmark pathology in Alzheimer’s disease) aggregation inhibits the expression of IST1 through the CEBPB-ANP32A-INHAT pathway, which hinders the formation of the ESCRT-III complex, inhibits the fusion of autophagosomes and lysosomes, and leads to autophagy disorder." (PMID 35463448, 2022). "Typical hallmarks of Alzheimer’s disease (AD) encompass extracellular deposition of amyloid-β plaques and intraneuronal aggregation of microtubule-associated protein tau, both of which are intricately linked with increased oxidative stress and neuronal inflammation." (PMID 35739972, 2022). "In addition to beta-amyloid proteins, the microtubule-associated protein tau has been heavily studied in its relation to Alzheimer’s disease." (PMID 36013492, 2022). "Moreover, abnormalities of the microtubule-associated protein tau (Tau) were observed in various neurodegenerative disorders, including Alzheimer’s disease (AD), Parkinson’s disease (PD), and Pick’s disease." (PMID 34445360, 2021). "Alzheimer disease (AD) is a neurodegenerative condition, characterized by the accumulation of insoluble forms of amyloid-beta (Aβ) and intracellular aggregation of the phosphorylated microtubule-associated protein tau (p-TAU)." (PMID 33653273, 2021). "Neurodegenerative disorders tauopathies, including the most common Alzheimer’s disease (AD), are characterized by abnormal hyperphosphorylation of microtubule-associated protein Tau that leads to the formation of neurofibrillary tangles (NFTs) and causes gain of toxic function." (PMID 34975454, 2021). "The microtubule associated protein tau is an intrinsically disordered phosphoprotein that accumulates under pathological conditions leading to formation of neurofibrillary tangles, a hallmark of Alzheimer’s disease (AD)." (PMID 33832539, 2021). "The microtubule-associated protein tau (MAPT) is involved in the establishment and maintenance of neuronal polarity and mutations in its gene led to nervous system diseases, such as Alzheimer’s disease, Pick’s disease, frontotemporal dementia and corticobasal degeneration." (PMID 32450814, 2020). "MAPT (p.A152T) has been linked with frontotemporal dementia and Alzheimer’s disease." (PMID 32079110, 2020). "A recent study showed that NUAK1 mediates the phosphorylation of the microtubule associated protein TAU on S356 and might be involved in tauopathies such as Alzheimer’s disease." (PMID 30327473, 2018). "MAPT encodes the Tau protein, a microtubule-binding protein in which aberrant accumulation of the phosphorylated form in affected neurons causes tauopathies, such as Alzheimer's disease and FTLD." (PMID 29774215, 2018). "The microtubule-associated protein tau is a critical mediator of neurotoxicity in Alzheimer’s disease (AD) and other neurodegenerative diseases, with functions in assembly and stabilization of microtubules, axonal transport, and neurite outgrowth in a phosphorylation-dependent manner." (PMID 30466464, 2018). "Other genes, ApoE and MAPT, are of particular interest because of their known association with dementia in other neurodegenerative diseases, such as Alzheimer's disease (AD) and atypical parkinsonian syndromes, including progressive supranuclear palsy and corticobasal degeneration." (PMID 30155299, 2018). "In subsequent work, we and others discovered that fly homologs of several genes at loci implicated by GWAS, including BIN1, PICALM, CD2AP, CELF1 and FERMT2, can interact with MAPT toxicity in vivo, providing mechanistic insight into their potential links with Alzheimer's disease risk in humans." (PMID 28151408, 2017).
Alzheimer disease (continued). "Alzheimer's disease (AD) is a progressive neurodegenerative disorder characterized by hyperphosphorylated microtubule-associated protein tau, neurofibrillary lesions composed of the β-amyloid peptide, aberrant oxidative and inflammatory processes, and disturbance in neurotransmission." (PMID 29234406, 2017). "The molecular characteristics of Alzheimer's disease (AD) are extracellular senile plaques and intracellular neurofibrillary tangles, composed of aggregated amyloid-β (Aβ) peptides and aggregates of the microtubule-associated protein tau, respectively." (PMID 27335169, 2016). "Also, although protein deposition of microtubule associated protein tau (MAPT) is a feature of Alzheimer’s disease (AD), MAPT gene mutations cause frontotemporal dementia (FTD) with Parkinsonism." (PMID 25426138, 2014). "H1/H2 haplotypes have been shown to affect expression and/or splicing of MAPT and have been associated with risk of several sporadic neurodegenerative disorders, including Alzheimer’s disease, progressive supranuclear palsy, corticobasal degeneration and Parkinson’s disease." (PMID 23951236, 2013). "Alzheimer's disease and other related neurodegenerative disorders known as tauopathies are characterized by the accumulation of abnormally phosphorylated and aggregated forms of the microtubule-associated protein tau." (PMID 21858230, 2011). "The microtubule-associated protein tau is the main component of paired helical filaments (PHF) which are aggregated structures found in neurofibrillary tangles (NFT) in the brains of patients with Alzheimer's disease (AD)." (PMID 21269457, 2011). "In Alzheimer’s disease, extracellular accumulation of the amyloid β peptide (Aβ) and intracellular aggregation of the microtubule associated protein tau may result from mechanisms involving chaperone proteins like the Hsps." (PMID 22654720, 2011). "Alzheimer's disease (AD) is a progressive neurodegenerative disease that is believed to be caused by the abnormal aggregation of harmful proteins including β-amyloid (Aβ) peptide and microtubule-associated protein tau." (PMID 21162742, 2010). "A prominent hypothesis for the aetiopathology of Alzheimer's disease is that in the presence of a β-amyloid load, individuals expressing a pathogenic form of tau protein (MAPT) are at increased risk for developing the disease." (PMID 17266761, 2007). "Microtubule stabilizers may have therapeutic value in neurodegenerative diseases such as Alzheimer's disease where hyper-phosphorylation of the microtubule associated protein tau results in the disintegration of microtubules and the formation of NFTs." (PMID 17551579, 2007). "This mechanistic link suggests that impaired microtubule formation may underlie the previously observed associations between DTI-ALPS and multiple Microtubule-Associated Protein Tau-related neurological diseases, including frontotemporal dementia, Parkinson’s disease, and Alzheimer’s disease." (PMID 41351017, 2025). "Genetic risk factors such as APOE ε4 and MAPT (rs242557) A allele are associated with amyloid and tau pathways and grey matter changes at both early and established stages of Alzheimer’s disease, but their effects on cortical morphology in young healthy adults remain unclear." (PMID 37693814, 2023). "Alzheimer’s disease (AD) is an age-related neurodegenerative disorder, characterized by the accumulation of proteinaceous aggregates and neurofibrillary lesions composed of β-amyloid (Aβ) peptide and hyperphosphorylated microtubule-associated protein tau, respectively." (PMID 35663578, 2022). "Alzheimer’s Disease is characterized by an aberrant misfolding and accumulation of beta-amyloid (Aβ) protein that forms extracellular deposits in the brain and by abnormal phosphorylation of the microtubule associated protein tau that forms intraneuronal aggregates of neurofibrillary tangles." (PMID 32784855, 2020).
Alzheimer disease (continued). "Alzheimer’s Disease (AD) is a neurodegenerative disorder characterized by the presence of two neuropathological features, namely the senile plaques, consisting of β-Amyloid peptides (Aβ), and the Neurofibrillary Tangles (NFTs), that contain highly phosphorylated microtubule-associated protein Tau." (PMID 31952362, 2020). "Finally, using a therapeutically relevant ASO targeting microtubule associated protein tau (MAPT), with the potential to treat Alzheimer’s disease and frontotemporal dementia, we confirmed that increasing convective forces can increase rostral CNS delivery of ASOs and imaging agents." (PMID 32771027, 2020). "Alzheimer’s disease is a devastating condition, neuropathologically characterized by the extracellular accumulation of amyloid-β in the form of plaques, and intracellular accumulation of hyperphosphorylated microtubule associated protein tau in the form of neurofibrillary tangles (NFTs)." (PMID 32705145, 2020). "The microtubule-associated protein tau undergoes transitions from soluble monomer to oligomer and subsequently into paired helical filaments that comprise the neurofibrillary tangles (NFTs), a pathological hallmark in Alzheimer’s disease (AD) and other neurodegenerative disorders." (PMID 31456657, 2019). "Alzheimer’s disease (AD) is a multifactorial neurodegenerative disorder resulting from proteinopathies characterized by the accumulation/ aggregation of β amyloid peptides (Aβ) and hyperphosphorylation followed by aggregation of microtubule-associated protein Tau." (PMID 30537985, 2018). "Alzheimer’s disease (AD) is an age-related neurodegenerative disorder characterized by progressive memory loss, intracellular neurofibrillary tangles (NFTs) composed of microtubule-associated protein tau, and extracellular amyloid plaques formed by amyloid-β (Aβ) aggregates in the brain." (PMID 29914543, 2018). "Similarly, the microtubule associated protein tau (MAPT) accumulates not only in neurons affected by Alzheimer’s disease (AD), but in PD and PDD, while mutations that increase the stability of tau result in frontotemporal dementia with parkinsonism (FTDP-17 (or FTD) [Spillantini and Goedert, 2013])." (PMID 27779468, 2016). "In Alzheimer Disease (AD), one observes two major aggregating proteins: Amyloid-beta (Aβ), which accumulates in the form of plaques mainly in the extracellular space and the microtubule associated protein Tau, which aggregates in the form of paired helical filaments (PHFs) intracellularly." (PMID 26691836, 2015). "Alzheimer’s disease, progressive supranuclear palsy, corticobasal degeneration and several other neurodegenerative diseases are characterized by the presence of intracellular aggregates of microtubule-associated protein tau leading to their grouping under the name of tauopathies." (PMID 26220942, 2015). "Neurodegenerative disorders may be distinguished upon presence and absence of disease specific protein aggregates e.g. α-synuclein in Parkinson, and amyloid precursor protein in Alzheimer's disease or the microtubule associated protein tau (MAPT or tau) as observed in for example AD, FTD, PiD, PSP." (PMID 19714246, 2009). "Although direct evidence demonstrating an increase in circulating MAPT mRNA levels in Alzheimer’s disease is limited, alterations in MAPT transcript structure have been identified in brain tissue." (PMID 41226373, 2025). "Protective relationships were similarly observed across proteinopathies, including FTD TDP-43 (C9orf72 and GRN), FTD tauopathy (MAPT), and Alzheimer’s disease, suggesting transdiagnostic relevance." (PMID 39816189, 2025). "Studies have shown that reducing MAPT expression protects against cognitive deficits in Alzheimer’s disease model mice." (PMID 40858609, 2025). "MAPT has been reported to be associated with the onset of neuropsychiatric disorders, such as SCZ, Alzheimer’s disease, and Parkinson’s disease." (PMID 40078531, 2025).
Alzheimer disease (continued). "Alzheimer’s disease and related tauopathies and amyloid diseases can also be initiated by direct genetic mutations, i.e., PSEN1 and MAPT." (PMID 37561137, 2024). "One of the most promising ASOs, MAPTRx, targets the microtubule-associated protein tau (MAPT) mRNA to reduce tau protein, accumulation of which is correlated with Alzheimer’s disease progression." (PMID 39352381, 2024). "Microtubule-associated protein tau (MAPT/tau) accumulates in a family of neurodegenerative diseases, including Alzheimer’s disease (AD)." (PMID 39266525, 2024). "So, further studies are needed on this patient to make a differential diagnosis of Alzheimer’s disease, sporadic FTD, or FTD with different genetic causes (MAPT or progranulin, for example)." (PMID 37763163, 2023). "Three of these predicted targets (i.e., APP, BACE1, and MAPT) were found to be highly interacting proteins (i.e., hub proteins) in the constructed Alzheimer’s disease PPI network." (PMID 37367890, 2023). "MAPT is central to the pathogenesis of multiple neurodegenerative disorders, including Alzheimer’s disease, Parkinson’s disease and some neuropsychiatric conditions." (PMID 37286376, 2023). "To further investigate the expression patterns and coordination of BAG2, STUB1, HSC70, and MAPT in Alzheimer’s disease patients, we performed a WGCNA analysis." (PMID 37251806, 2023). "We performed a Weighted Gene Co-expression Network Analysis (WGCNA) to investigate the expression patterns and coordination of BAG2, STUB1, HSC70, and MAPT in Alzheimer’s disease (AD) patients." (PMID 37251806, 2023). "An important aspect is related to the binding properties of [18F]flortaucipir: its retention has been found in vivo to correlate strongly with post-mortem tau pathology in MAPT R406W mutant gene carriers and with Alzheimer’s disease-related tau pathology." (PMID 37238166, 2023). "Further, we looked into the expression of a specific splice form of the MAPT gene enriched in the adult brain, the 4R TAU, which is associated with different tauopathies such as frontotemporal dementia and Alzheimer’s disease." (PMID 36361956, 2022). "Comparison with an in-house protein signature of Alzheimer’s disease brains indicated that the observed alterations in RNA processing and oligodendrocyte function are distinct for the frontotemporal dementia MAPT subtype." (PMID 35799292, 2022). "Another interesting example is the microtubule-associated protein tau, an IDP that is found as intracellular solid aggregates in Alzheimer’s disease." (PMID 35898309, 2022). "Alzheimer’s disease (AD) involves pathological processing of amyloid precursor protein (APP) into amyloid-β and microtubule associated protein Tau (MAPT) into hyperphosphorylated Tau tangles leading to neurodegeneration." (PMID 36151233, 2022). "Alzheimer's disease (AD) is a complex neurodegenerative disease which is characterized by the formation of extracellular amyloid beta (Aβ) plaques and intracellular tau/MAPT aggregates in the brain." (PMID 35349763, 2022). "The Tau/MAPT was also enriched in the “Tau pathology in Alzheimer disease” pathway together with protein phosphatase; PPM1F was identified in the pathway as the PP2C group with the highest expression in the SOY1.5 group." (PMID 35804531, 2022). "Upregulation of phosphorylated microtubule-associated protein tau (MAPT) and consequently altered mitochondrial functions are associated with Alzheimer’s disease; in cancer, MAPT overexpression is linked to poor prognosis and drug resistance." (PMID 33686350, 2021). "This is the case for MAPT mutations, which cause the FTLD tau subtype, and GRN and TREM2 mutations, which have been associated with the TDP-43 subtype and Alzheimer's disease." (PMID 35115992, 2021). "Examples of these cohorts are the GENetic Frontotemporal Dementia Initiative (GENFI; genotype data for GRN, MAPT, and C9ORF72 genes) and the Genetic and Environmental Risk in Alzheimer’s Disease (GERAD) Consortium (whole exome sequences)." (PMID 34559060, 2021).
Alzheimer disease (continued). "Pathologic phosphorylation and subsequent aggregation of the microtubule binding protein tau (MAPT) is believed to play a central role in driving cognitive decline in Alzheimer's disease (AD) and related tauopathies." (PMID 33893219, 2021). "MAPT is mainly expressed in nerve cells, and more commonly studied in geriatric diseases such as various neurodegenerative diseases including Alzheimer’s disease." (PMID 33962640, 2021). "Suppression of human MAPT has been proposed as a potential therapy for tauopathies, including Alzheimer’s disease and frontotemporal dementia." (PMID 32771027, 2020). "The model carries three mutations related to familial Alzheim’s disease (FAD): APP Swedish, MAPT P301L, and PSEN1 M146 V." (PMID 31987051, 2020). "Through haplotype‐stratified association analyses using data from the Alzheimer's Disease Genetics Consortium (ADGC) on 18,841 participants, we identified 11 loci with MAPT H1– or H2–specific AD risk association." (PMID 32400971, 2020). "However, since one hallmark of AD is hyper-phosphorylation of the microtubule-associated protein Tau, this finding offers a therapeutic implication for TMANO in Alzheimer disease." (PMID 32244373, 2020). "This chromosomal region also contains the MAPT gene, which plays a role in Alzheimer’s disease, Parkinson’s disease, and frontotemporal dementia." (PMID 32963231, 2020). "Alzheimer’s disease is also associated with CMA since the beta-amyloid peptide (Aβ), the microtubule-associated protein Tau or the Regulator of calcineurin 1 (RCAN1) are involved in Alzheimer’s disease and are dysregulated when CMA is altered." (PMID 32792938, 2020). "The hyperphosphorylation of the microtubule-associated protein tau (MAPT) has been implicated in various neurological diseases, including Alzheimer’s disease." (PMID 32575375, 2020). "Alzheimer disease (AD) is neuropathologically characterized by extracellular amyloid plaques composed of amyloid β (Aβ) peptides and intracellular neurofibrillary tangles (NFTs) constituted of microtubule associated protein tau." (PMID 32493451, 2020). "Tau protein is encoded by the microtubule associated protein Tau (MAPT) gene and can aggregate to form neurofibrillary tangles that are usually shown in Alzheimer’s disease (AD) and other tauopathies." (PMID 32290247, 2020). "In a large study from Genetic and Environmental Risk for Alzheimer's Disease (GERAD1) consortium, the MAPT H2 haplotype–tagging variant was found to have association with reduced AD risk." (PMID 32400971, 2020). "The first-ranked gene FMR1 was proved to be associated with mental diseases like mental retardation and autism, and five other genes (APP, SNCA, MAPT, SIRT2, APOE) are known to be associated to Alzheimer's disease." (PMID 32038710, 2019). "The nuclear hub network enrichment was driven by genes implicated in Alzheimer’s disease (APOE), non-alcoholic drug-related phenotypes (RAB4B-EGLN2), and cognitive ability (LRRN2 and MAPT)." (PMID 31171808, 2019). "Some of these interesting genes, such as MAPT, CASP2, and PSEN2, are linked with important aspects of Alzheimer’s disease, such as dementia, increase cell death, and deposition of amyloid-beta proteins in Alzheimer’s disease brains." (PMID 27901073, 2016). "Other authors observed that the MAPT H1 haplotype enhances the overall α-synuclein deposition type pathology in dementia with Lewy Body and Alzheimer’s disease." (PMID 27147968, 2016). "Several neurodegenerative diseases are associated with the hyperphosphorylation, misfolding, and aggregation of the microtubule-associated protein tau, including progressive supranuclear palsy (PSP), frontotemporal dementia, and Alzheimer's disease." (PMID 27697694, 2016). "In the Huntington's disease, parkingson's disease, oxidative phosphorylation, and alzheimer's disease pathways, CLTC is involved in inflammatory myofibroblastic tumors and lower expression of MAPT is associated with HER2 overexpression." (PMID 23369492, 2013).